RAD54L (RAD54 like)
Description:
Multifunctional ATPase that plays a role in homologous recombination (HR) which is a major pathway for repairing DNA double-strand breaks (DSBs), single-stranded DNA (ssDNA) gaps, and stalled or collapsed replication forks. Acts as a molecular motor during the homology search and guides RAD51 ssDNA along a donor dsDNA thereby changing the homology search from the diffusion-based mechanism to a motor-guided mechanism. Also plays an essential role in RAD51-mediated synaptic complex formation which consists of three strands encased in a protein filament formed once homology is recognized. Once DNA strand exchange occured, dissociates RAD51 from nucleoprotein filaments formed on dsDNA (By similarity).
Synonyms: hHR54; hRAD54; RAD54A; HR54
Tractability: PROTAC: ubiquitination databases record sites on it.
Target class: Enzyme
Gene: Protein-coding gene on chromosome 1 (46,246,461 to 46,278,482, forward strand). Ensembl gene ENSG00000085999.
Subcellular location: Nucleus
Subcellular location (Human Protein Atlas): Nucleoplasm
Gene Ontology:
Molecular function: ATP hydrolysis activity; ATP-dependent activity, acting on DNA; ATP-dependent DNA/DNA annealing activity; protein binding; DNA translocase activity; ATP binding
Biological process: double-strand break repair via homologous recombination; DNA recombination; DNA repair; meiotic cell cycle; reciprocal meiotic recombination
Cellular component: nucleoplasm; protein-containing complex; site of double-strand break; nucleus
Genetic constraint (gnomAD): Loss-of-function variants: 73 observed, 94.35 expected, observed/expected ratio (o/e) 0.77, 90% interval 0.64 to 0.94. The upper end of that interval is the gene's LOEUF score, 0.94, which puts it in group 3 of 6, group 1 being the genes least tolerant of losing a copy. Missense variants: 887 observed, 991.69 expected, observed/expected ratio (o/e) 0.89, 90% interval 0.85 to 0.94. Synonymous variants: 304 observed, 369.14 expected, observed/expected ratio (o/e) 0.82, 90% interval 0.75 to 0.91.
Homologues: Orthologues: chimpanzee RAD54L (99% identical), macaque RAD54L (98% identical), pig RAD54L (95% identical), guinea pig RAD54L (95% identical), dog RAD54L (95% identical), mouse Rad54l (94% identical), rabbit RAD54L (94% identical), rat Rad54l (94% identical), tropical clawed frog rad54l (80% identical), zebrafish rad54l (79% identical), Drosophila melanogaster okr (55% identical), Caenorhabditis elegans rad-54.L (55% identical). Paralogues in human: RAD54B (43% identical), RAD54L2 (24% identical), ATRX (24% identical), CHD4 (24% identical), ERCC6 (23% identical), CHD5 (23% identical), CHD7 (23% identical), CHD8 (23% identical), CHD1 (23% identical), CHD2 (23% identical), CHD3 (23% identical), CHD9 (23% identical), and 18 more.
Diseases named in the same sentence as RAD54L in open-access papers:
RAD54L is named in the same sentence as 45 diseases in open-access papers, as found by Europe PMC text mining. Sharing a sentence is not in itself a finding about the gene and the disease. The quoted sentences say what the papers report.
breast carcinoma (14 papers, 2010 to 2025). "The RAD54L gene (Case 2) was located at 1p32, and its mutation may be associated with breast cancer, colon cancer, lymphoma, and meningioma." (PMID 36686750, 2022). "This patient also harboured a lpVUS in the RAD54L gene, which has been reported in a breast cancer patient from South Africa (Accession: RCV002226353.1, ClinVar)." (PMID 40627234, 2025). "Elevated expression of RAD54L is detected in carcinomas of the breast, colon, lymphoma and meningioma; however, its role in MM pathogenesis is unknown." (PMID 35689754, 2022). "Elevated expression of RAD54L was identified in colon and breast cancer, lymphoma and meningioma." (PMID 28458781, 2017). "To exclude that this effect was specific to HeLa cells, we generated RAD54L/RAD51AP1 single KO and DKO cells in the Hs578T breast cancer cell line and tested these cells in olaparib cell survival assays." (PMID 35652094, 2022). "Mutations in BRCA1/2 genes, especially germline variations, along with other Fanconi anaemia (FA) pathway genes (such as NBN, RAD54L, ATM), are prototypic molecular alterations that confer HRD in breast cancer." (PMID 34465315, 2021). "Interestingly, most of these key repair genes, including BRCA1, RAD51, RAD54L and BLM, were also identified in this study as E2F1 targets in breast cancer." (PMID 27666291, 2016).
Fanconi anemia (11 papers, 2016 to 2025). Fanconi anemia (FA) is a hereditary DNA repair disorder characterized by progressive pancytopenia with bone marrow failure, variable congenital malformations and predisposition to develop hematological or solid tumors. "For example, targeting of genes known to play roles in DNA damage repair (DDR), including RAD54L, MUS81, and 16 proteins in the Fanconi Anemia pathway, strongly sensitized cells to camptothecin, which generates protein–DNA adducts." (PMID 39903505, 2025). "Additionally, Su-Dhl-4 cells treated with entinostat or tazemetostat also showed downregulation of RAD51, RAD54L, BRCA2, and three Fanconi anemia genes (FANCA, FANCB, and FANCM)." (PMID 31829282, 2019).
lymphoma (6 papers, 2013 to 2023). A malignant (clonal) proliferation of B- lymphocytes or T- lymphocytes which involves the lymph nodes, bone marrow and/or extranodal sites. "Although research on RAD54L in humans is limited, RAD54 mutations in breast and colon carcinomas and some lymphomas have been reported." (PMID 33261027, 2020). "Moreover, the RAD54L gene has been flagged as to be a candidate cosuppressor in breast or colon carcinomas, lymphomas, and meningiomas, supporting its role in tumorigenesis." (PMID 37298600, 2023).
ovarian carcinoma (5 papers, 2017 to 2024). A malignant neoplasm originating from the surface ovarian epithelium. "Despite the lack of a significant correlation between RAD54L expression and overall survival, higher MYBL2 and RAD54L expression tended to predict a worse prognosis in patients with ovarian cancer." (PMID 38424195, 2024). "In another study, the upregulation of Polθ and its positive correlation with expression of many DNA repair genes including TOPBP1, BLM, RAD54L, FANCI, BRCA1, FANCD2, ATAD5 was reported in HR-deficient epithelial ovarian cancer cells." (PMID 34762643, 2021). "Moreover, E2F1 transcriptionally regulates the expression of the oncogenes MYBL2 and RAD54L, driving ovarian cancer progression." (PMID 38424195, 2024). "NSUN2 is aberrantly upregulated in ovarian cancer and promotes the malignancy of ovarian cancer through regulating the expression of the oncogenic driver E2F transcription factor 1 (E2F1) in an m5C-dependent manner, and E2F1 facilitates the transcription of NSUN2 as well as MYBL2 and RAD54L." (PMID 38424195, 2024).
prostate carcinoma (5 papers, 2015 to 2023). A carcinoma that arises from epithelial cells of the prostate gland. "RAD54L is now considered a predictive biomarker for the use of olaparib in patients, particularly in prostate carcinoma." (PMID 37298600, 2023). "We verified the results in MCF7 cells by determining the effect of RAD54L+RAD54B depletion in two additional cell lines: the prostate cancer cell line, PC-3 and the triple-negative breast cancer cell line, MDAMB231." (PMID 25765654, 2015). "Moreover, there is good evidence from prostate cancer that the PARPi olaparib is effective in tumours with alterations in RAD51C, RAD51D, CHEK2, PALB2, RAD54L, and BARD1." (PMID 34680387, 2021).
choroid plexus carcinoma (4 papers, 2019 to 2021). A malignant neoplasm arising from the choroid plexus. "Upregulation of HRR pathway and RAD54L expression in choroid plexus carcinoma to reduce replication stress and genotoxic damage for tumor progression." (PMID 33628633, 2021). "Higher expression of RAD54L correlates with poor prognosis of patients with glioblastoma and choroid plexus carcinoma." (PMID 33658396, 2021). "(ii) Mouse/human genomic screenings searching for driver oncogenes of Choroid Plexus Carcinomas identified the syntenic NF-YC, TAF12 and RAD54L genes, with the formers having the greatest impact on tumor development." (PMID 31506469, 2019).
glioblastoma (4 papers, 2020 to 2024). The most malignant astrocytic tumor (WHO grade IV). "Recent evidence has shown that RAD54L regulation contributed to radioresistance and neoplastic transformation in glioblastoma and head and neck cancer." (PMID 38421735, 2024). "Interestingly, two hub genes, including RAD54L, were shown to play an important role in the pathological mechanism of glioblastoma (GBM) in our study." (PMID 32391047, 2020).
bladder cancer (3 papers, 2020 to 2022). "High RAD54L expression was linked to a shorter survival of patients with bladder cancer." (PMID 35656315, 2022). "Our results suggest that, E2F1 and RAD54L could be used as diagnostic markers for bladder cancer progression and represent potential therapeutic targets." (PMID 33261027, 2020). "The expression levels of EME1, RAD51, RAD51AP1, and RAD54L genes were significantly higher in high grade bladder cancer and invasive bladder cancer (p < 0.05) than in low grade bladder cancer and superficial bladder cancer." (PMID 35559013, 2022). "In bladder cancer, the transcription factor E2F1 directly activates RAD54L, regulating DDR, and is linked to poor prognosis." (PMID 35559013, 2022). "Taken together, these results demonstrate that the expression of E2F1 and RAD54L is significantly correlated with the progression of bladder cancer, and strongly correlated with its recurrence." (PMID 33261027, 2020). "Tissue microarrays (TMAs) were used to determine the role of high expression levels of E2F1 and RAD54L in cancer progression and poor prognosis of bladder cancer patients." (PMID 33261027, 2020). "In gene expression analysis of bladder cancer patients, the survival of patients with high RAD54L expression was shorter with cancer progression than in patients with low RAD54L expression." (PMID 33261027, 2020). "This study also confirmed that DNA breaks are repaired by RAD54L induced by E2F1 in bladder cancer cells treated with MMC." (PMID 33261027, 2020). "Based on the expression analysis of 1,027 genes, we divided 102 bladder cancer patients into a high RAD54L cluster and a low RAD54L cluster." (PMID 33261027, 2020). "Therefore, we sought to determine the association of bladder cancer recurrence with the expression of E2F1 and RAD54L." (PMID 33261027, 2020). "Our study found a substantial correlation between RAD51AP1, RAD54L, and EME1 gene expression and bladder cancer proliferation, Th2, and wound healing scores." (PMID 35559013, 2022). "Immunohistochemical (IHC) evaluation was used to determine protein expression levels of E2F1 and RAD54L in 17 patients with recurrent bladder cancer and 11 patients with non-recurrent bladder cancer." (PMID 33261027, 2020). "In particular, it is unclear whether there is a correlation between RAD54L and E2F1 in bladder cancer cells." (PMID 33261027, 2020). "Therefore, RAD54L, a DNA repair gene in addition to E2F1, can be used as a biomarker for bladder cancer prognosis." (PMID 33261027, 2020).
lung carcinoma (3 papers, 2019 to 2022). "To exclude that this effect was specific to HeLa cells, we depleted RAD51AP1 and/or RAD54L in A549 lung cancer cells." (PMID 35652094, 2022). "RAD54L is overexpressed in all lung cancer datasets and PAH dataset." (PMID 31867044, 2019).
colorectal cancer (2 papers, 2022). A primary or metastatic malignant neoplasm that affects the colon or rectum.
head and neck squamous cell carcinoma (2 papers, 2021 to 2024). A squamous cell carcinoma that arises from any of the following anatomic sites: lip and oral cavity, nasal cavity, paranasal sinuses, pharynx, larynx, and salivary glands. "It is reported that Oct4 promotes stemness in head and neck squamous cell carcinoma via modulating PSMC3IP and RAD54L." (PMID 38430256, 2024).
melanoma (2 papers, 2007 to 2025). A malignant, usually aggressive tumor composed of atypical, neoplastic melanocytes.
sarcoma (2 papers, 2022 to 2023). A usually aggressive malignant neoplasm of the soft tissue or bone. "No HRR mutations were detected in LGSOC, sarcoma, and borderline serous tumors in this study; 2.7% (4/46) BRCA1 and 1.2% (1/46) other HRR variants were reported in LGSOC in the GOG 218 study, and RAD54L was recently reported in one of six LGSOC in a Japanese study." (PMID 35186721, 2022).
triple-negative breast carcinoma (2 papers, 2015 to 2023). An invasive breast carcinoma which is negative for expression of estrogen receptor (ER), progesterone receptor (PR), and human epidermal growth factor receptor 2 (HER2). "Five other members belonging to the family of homologous recombination repair genes were upregulated by PAC in triple-negative breast-cancer cells (RAD54L, XRCC3, RAD51D, FEN1, and TOP3A) but only RAD54L is common in both types of cell lines (MCF-7 and MDA-MB-231)." (PMID 37298600, 2023).
autoimmune disorders (1 paper, 2025). "Although there are no reports of any connections between RAD54L and either neurodevelopmental or immune/autoimmune disorders, the gene is expressed in the brain and immune cells, with the highest levels found in EB-transformed lymphoblasts (GTEx database, Release 6)." (PMID 40894167, 2025).
bladder tumor (1 paper, 2023). "have found that high Rad54L expression promotes abnormal bladder tumor cell proliferation by changing the cell cycle and cell senescence." (PMID 38152367, 2023).
Bloom syndrome (1 paper, 2025). Bloom syndrome (BSyn) is a rare chromosomal breakage syndrome characterized by a marked genetic instability associated with pre- and postnatal growth retardation, facial sun-sensitive telangiectatic erythema, increased susceptibility to infections, and predisposition to cancer. "Elevated expression of KLF5 promotes the expression of key HRR pathway genes, including RAD51, checkpoint kinase 1 (CHEK1), RAD54 like (RAD54L), essential meiotic structure-specific endonuclease 1 (EME1), and Bloom syndrome (BLM), thereby reversing the HRR suppression mediated by PARPi." (PMID 40032852, 2025).
gastric tumor (1 paper, 2022). "Through IHC analysis, we found in gastric tumor tissues (n = 10) that the protein expression of most of the genes in the DRGS, except for PARPBP, EME1, and RAD54L, was significantly increased." (PMID 35676932, 2022).
meningeal tumors (1 paper, 2021). "Similarly, polymorphisms detected in the RAD54L are a genetic marker associated with meningeal tumors’ development." (PMID 34068918, 2021).
myeloma (1 paper, 2022). "For the first time, our results demonstrate that up-regulation of RAD54L might play a key role, at least in part, in MM pathogenesis by activating myeloma cell growth, inhibiting apoptosis and impairing cell cycle progression." (PMID 35689754, 2022).
pancreatic cancer (1 paper, 2019). "SNP in tumor suppressor RAD54L is important for the development of pancreatic cancer, but this polymorphic gene may be identified with the development of BRCA." (PMID 31311202, 2019).
prostate adenocarcinoma (1 paper, 2013). "Indeed, the RAD54 ortholog, RAD54L, is strongly down-regulated in LNCAP (prostate adenocarcinoma) cells treated with vorinostat." (PMID 23531409, 2013).
tumor (35 papers, 2007 to 2025). "RAD54L, known for its role as an oncogene, is associated with tumor progression and poor prognosis in multiple cancers, and has potential as a therapeutic target." (PMID 40227503, 2025). "The study found RAD51AP1, RAD54L, and EME1 to be hub genes in HR patterns associated with immunotherapy response and tumor progression." (PMID 35559013, 2022). "The potential role of PSMC3IP and RAD54L in tumor development is supported by significantly higher expression levels of these genes in HNSCC than in normal tissues." (PMID 34079088, 2021). "The mRNA and protein expression levels of UHRF1, EZH2, TTF2, WHSC1 and RAD54L significantly correlated with tumor stage in NSCLC patients." (PMID 33658396, 2021). "HRR pathway is up-regulated in LUAD, among which the expression of RAD54L was found to be significantly differentially expressed in T1 stage tumor tissue." (PMID 33628633, 2021). "Results showed that four of these hub proteins (AURKA, CDC45, ESPL1, and RAD54L) were over-expressed in all tumor subtypes." (PMID 32932728, 2020). "As in the human tumor cell experiments, only a small fraction of the RAD51 foci seen in Rad54l−/−Rad54b−/− cells were associated with an RPA focus." (PMID 25765654, 2015). "Additionally, high mRNA expression levels of genes such as RAD54L (p = 3.3 × 10−6), MAST2 (p = 4.1 × 10−2), and CCHCR1 (p = 1.4 × 10−2) were associated with shorter DFS, further highlighting their role in tumor aggressiveness." (PMID 40227503, 2025). "Similarly, alterations in DNA damage response genes such as ATM, CDK12, and those of the RAD family (RAD51C, RAD54L) were observed across multiple tumour types." (PMID 37120671, 2023). "Furthermore, expression levels of UHRF1, EZH2, TTF2, WHSC1 and RAD54L transcripts correlated significantly with the tumor stages of NSCLC patients (P<0.05)." (PMID 33658396, 2021). "Among them, RAD54L might be the biggest factor affecting tumor grade (one-way ANOVA: 56.778, P < 0.001; spearman correlation: 0.504, P < 0.001; distance correlation: 0.522, P < 0.001)." (PMID 31134129, 2019). "The specific HRR mutations identified in the 21 tumour samples were: BRIP1 (n = 5), CDK12 (n = 3), RAD54L (n = 2), RAD51B (n = 2), RAD54L rearr (n = 1), ATM rearr (n = 1), FANCA rearr (n = 1), FANCD2 (n = 1), FANCL rearr (n = 1), FANCL (n = 1), RAD51C (n = 1), RAD52 del (n = 1), XRCC3 rearr (n = 1)." (PMID 30353044, 2018). "Moreover, RAD54L expression significantly correlated with tumor stages of patients with NSCLC." (PMID 33658396, 2021). "Knockdown of Oct4 A isoform reduced self-renewal capacity in HNSCC and led to partial tumor cell radiosensitization caused by transcriptional downregulation of the cell cycle checkpoint kinases CHK1 and WEE1 and homologous recombination (HR) repair genes PSMC3IP and RAD54L." (PMID 34079088, 2021). "MYBL2 and RAD54L have been demonstrated to be downstream targets of E2F1, which has been demonstrated to be involved in tumor growth and metastasis." (PMID 38424195, 2024).